OR4A8 (olfactory receptor family 4 subfamily A member 8 (gene/pseudogene))
Description:
Odorant receptor.
Synonyms: OR4A8P
Gene: Protein-coding gene on chromosome 11 (54,682,877 to 54,683,821, forward strand). Ensembl gene ENSG00000225997.
Subcellular location: Cell membrane
Pathways (Reactome):
Sensory Perception: Expression and translocation of olfactory receptors
Homologues: Orthologues: dog OR4A39 (71% identical), mouse Or4a39 (70% identical), rat Olr703 (69% identical), rat Or4a78 (67% identical), mouse Or4a78 (67% identical), mouse Or4a80 (66% identical), mouse Or4a73 (65% identical), rat Olr716 (65% identical), rat Or4a73 (64% identical), rat Or4a71 (63% identical). Paralogues in human: OR4A5 (75% identical), OR4A16 (68% identical), OR4A47 (62% identical), OR4A15 (60% identical), OR4C46 (55% identical), OR4C15 (55% identical), OR4C3 (55% identical), OR4C13 (53% identical), OR4C5 (53% identical), OR4C12 (52% identical), OR4C11 (51% identical), OR4X2 (50% identical), and 116 more.